B2M (beta-2-microglobulin)
Diseases named in the same sentence as B2M in open-access papers (continued):
Sharing a sentence is not in itself a finding about the gene and the disease.
tumor (continued). "In both Yummer 1.7 and MC38 B2M KO models, the first signs of active tumor inhibition were observed 8 days after treatment with mIL12 mRNA." (PMID 40321762, 2025). "Very few apoptotic TUNEL+ cells were found on the surface of PBS-treated tumors or CpG ODN-treated B2M KO tumor after four daily injections." (PMID 41109214, 2025). "Next, we assessed B2M protein expression in cHL tissue sections to correlate the tumor cell expression patterns to aberrations of the genomic loci of these genes." (PMID 40198333, 2025). "After that, a group of primary tumor cells acquired six additional mutations (in genes AKT1, BCL9L, B2M, FBXW7, MUTYH, RSPO2)." (PMID 38685065, 2024). "B2M is widely expressed in most nucleated cells, such as immune cells, with stromal cells surrounding tumor cells exhibiting strong B2M expression." (PMID 39453509, 2024). "Some studies with human tumor specimens and animal models have demonstrated that downregulation of B2M and HLA give rise to tumors with poor prognosis and resistance to CPI therapy." (PMID 38455061, 2024). "The triple combination of tumor PD-L1, intratumoral CD8+ cells and pretreatment B2M expression improved the prediction score over the single marker or dual combination of tumor PD-L1 and intratumoral CD8+ cell infiltration." (PMID 38455061, 2024). "Similar studies in mice implanted with MC38 B2m KO cells indicated abrogated tumor response to either immune checkpoint inhibitor, contrasting with a significant decrease in tumor growth observed in mice harboring MC38 wt tumors." (PMID 38427670, 2024). "We have also investigated combinations of pretreatment B2M and HLA levels relative to tumor PD-L1 expression and CD8+ tumor infiltration, which are known biomarkers for response to checkpoint inhibitor therapy." (PMID 38455061, 2024). "Some studies have reported that B2M has a significant relationship with the tumor-immune microenvironment and plays a critical role in tumor progression, patient prognosis, and immunotherapy of gliomas." (PMID 38971807, 2024). "As expected, deletion of B2m in either EMT6 or MC38 led to complete loss of H2Dd and H2Kd expression, preventing tumor recognition and elimination by CD8+ T cells." (PMID 38427670, 2024). "We observed increased expression of B2M in the WT tumor cells treated with VC, which was reduced in the TET2-KO cells." (PMID 39388288, 2024). "When decreasing the leading and highly overexpressed genes HLA-A in tumor cells and B2M for the CosMx HCC dataset, we model the quantifiable transition of tumor cells (large nuclei, cellular atypia, variation in nuclear size) toward normal cells." (PMID 38341653, 2024). "After establishment of robust and reproducible IHC assays for B2M and HLA-A, we utilized these to examine the expression of B2M and HLA-A on tumor cells of diverse cancer types." (PMID 38455061, 2024). "The tumor cell membrane has a transmembrane-attached peptide-MHC class I receptor maintained by beta-2-microglobulin(B2M)." (PMID 38590525, 2024). "Only the expression of β2 microglobulin (B2M) was found significantly lower in tumor tissues compared to healthy colon samples in the analyzed data sets." (PMID 39075115, 2024). "TAP1, TAP2, TAPBP, and β2-microglobulin (B2M) are critical proteins involved in the class I MHC antigen presentation process in virus-infected or tumor cells." (PMID 39388288, 2024). "Among stromal fibroblast cells, ITGAV, ITGA1, ITGB1, and ITGB5 were significantly upregulated following IO and, notably, isolated tumor cells found in the stroma showed upregulation of B2M, VIM, ITGA5, ITGB2, and ITGA3." (PMID 39639369, 2024).
tumor (continued). "For this, we have developed robust, reproducible assays for IHC staining and quantification of B2M and HLA-A expression on tumor cells." (PMID 38455061, 2024). "In cancer patients, B2M gene alterations have been related to MHC class I deficiency and loss of β2M protein expression, facilitating tumor cell escape from the host's immune control." (PMID 38888359, 2024). "We found the blood markers associated with lymphoma tumor burden including lactate dehydrogenase (LDH) and beta 2 microglobulin (β2M) were also informative with 38.6% positivity for LDH and 30.8% for β2M based on the clinical cut-offs in the current study." (PMID 38313801, 2024). "Complementary to these quantification results, normal liver cells acquire a remarkably malignant appearance (i.3) when driven by edited genes of interest (increase in nuclear area and overexpression of B2M) toward the tumor spectrum." (PMID 38341653, 2024). "Analysis of the 53 overlapping genes identified an enrichment for proteins with tumor-intrinsic immune functions such as B2M, MHC class I proteins, and interferon family members." (PMID 38791964, 2024). "We observed an upregulation of β2-microglobulin (B2M) expression in those cancer-cell-intrinsic inflammatory tumor subclusters (clusters with top inflammation score) vs. those with the lowest scores (log2FC = 0.91)." (PMID 36973268, 2023). "Anti-tumour immune responses require adequate antigen presentation, which is coordinated by several genes, including B2M." (PMID 36870947, 2023). "In the presence of B2M/beta 2 microglobulin, immunogen-presenting cells show predominantly viral and tumor-derived peptides for identification by the alpha-beta T cell receptor (TCR) on HLA-A-restricted CD8-positive T cells." (PMID 36999015, 2023). "Tumor cells can avoid processing and presenting tumor antigens by silencing or altering the expression of antigen-presenting machinery, beta-2-microglobulin (B2M), or major histocompatibility complex (MHC) molecules." (PMID 37465684, 2023). "Overall, HLA-E and -F coexpression correlated with high levels of HLA-A, TAP1/2 and B2M transcripts across tumor types." (PMID 38318504, 2023). "B2MG encodes Beta-2-microglobulin, which is a serum protein found in association with the major histocompatibility complex (MHC) class I heavy chain tumor marker." (PMID 38069262, 2023). "To assess the alterations of CTL cytotoxicity towards tumor cells aroused from B2M expression change induced by D‐2HG and αKG, we co‐cultivated CD8+ T cells with Renca cells treated with αKG and D‐2HG alone or together." (PMID 37526345, 2023). "To further explore the connections between B2M expression and CD8+ T cell‐mediated anti‐tumor effects, we constructed B2M‐Sh1 and B2M‐Sh2 plasmids and verified their knockdown efficiency using qPCR and western blots." (PMID 37526345, 2023). "By contrast, only three tumors (one individual) demonstrated methylation at HLA-B, and only one tumor had HLA-C or B2M methylated." (PMID 36585450, 2023). "A total of 13 out of 21 (62%) patients with B2MMUT tumours had biallelic B2M alterations, 4 (19%) had potentially biallelic alterations and 4 (19%) had non-biallelic alterations." (PMID 36631610, 2023). "Downregulation of B2M in the MHC-I/TCR complex allows for the tumour cells to avoid immune destruction mechanisms." (PMID 36980527, 2023). "Nevertheless, this modification of MM3 TILs enabled the cytotoxicity of both parental MM3 cells and B2M KO tumor cells in vitro, which correlated with IFN-γ secretion into the medium." (PMID 36765608, 2023). "The MHC I complex, including the beta-2-microglobulin (B2M) subunit, presents tumor-generated peptides at the cell surface, which can be recognized by cytotoxic CD8+ T cells." (PMID 37371815, 2023). "Confirming screen robustness, sgRNAs targeting genes required for T cell function were depleted from the tumor, including Tap1, B2m, CD47, Jak1, and Jak3." (PMID 38099496, 2023).
tumor (continued). "Depending on its expression level, HDAC2 can positively or negatively control the transcriptional activity of CIITA and B2M, which, in turn, can be differently regulated within the tumor microenvironment." (PMID 37046620, 2023). "Intriguingly, B2M, which is part of the MHC class I system, promotes numerous forms of resistance and is associated with tumor escape." (PMID 37046620, 2023). "The expression of class I HLA molecules, which are responsible for antigen presentation to tumor-killing T-cells, including HLA-A, HLA-B, HLA-C, HLA-E, HLA-F, and B2M, was downregulated in 7, 8, 5, 10, 5, and 14 patients, respectively." (PMID 37152992, 2023). "Similar to the findings in proteomics and immunohistochemistry, the expressions of MHC class I and B2M were mostly significantly downregulated in tumor cells." (PMID 37098551, 2023). "B2M is a component of the MHC class I complex, and B2M expression on tumor cells protects them from phagocytosis." (PMID 36973268, 2023). "B2M plays an important role in supporting MHC class I molecules to present tumor-specific peptide antigens to T cells." (PMID 37465684, 2023). "Patients in the upper tertile of B2M expression in tumor, were found to have significantly prolonged PFS and OS (Punadjusted = 0.010 and P = 0.021, respectively) to immunotherapy." (PMID 37057033, 2023). "Mouse PyMT tumor cells that were forced to undergo EMT through the upregulation of EMT-TFs ZEB1 or SNAIL in vitro also showed a marked decrease in B2M protein, a crucial co-factor for MHC I stability and antigen presentation on the cell surface." (PMID 38067396, 2023). "Altogether, these results indicate that B2M overexpression inhibits tumor growth by augmenting CD8+ T cell infiltration and cytotoxic effects." (PMID 37526345, 2023). "The results showed that stromal tumor-infiltrating lymphocytes (TILs) percent and the expression levels of CD44, B2M, PTPN11, and TRIM74 were associated with DFS in NPC patients." (PMID 36107539, 2022). "An in vivo study using the Ma-Mel-86b tumor xenograft model in nude mice also showed that the intratumoral injection of B2M-carrying vectors resulted in restoring regular HLA class I expression." (PMID 36046045, 2022). "It is interesting to note that among the cancer-hallmark genes, two genes, H3F3B (p < 0.0001, adj-p < 0.0001) and B2M (p = 0.0003, adj-p = 0.018), were enriched with alterations in EV-DNA, while 55 genes were enriched with alterations in tumor DNA." (PMID 35892848, 2022). "B2M was involved in immune reactions, such as mucosal immunity, tumor surveillance, and immunoglobulin homeostasis." (PMID 34825737, 2022). "An APM gene expression signature of 18 different genes (including B2M, HLA A/B/C and TAP 1/2) has been combined with tumor mutation burden in an algorithm referred to as tumor immunogenicity score." (PMID 36615128, 2022). "We also find a prominent in situ activation of CD4+ T cells in WT and B2m-/- B16 tumor-bearing lungs." (PMID 36733396, 2022). "As we expected, the cytotoxicity of NK cells was remarkably enhanced against several tested tumor cells with downregulated HLA-I expression due to reduced TAP or B2M expression." (PMID 36612246, 2022). "We found that the expression level of ADARB1, CXCL12 and TABPB were higher in recurrent tumor tissues, whereas the expression level of B2M was lower in recurrent tumor tissues." (PMID 35177985, 2022). "Tumor cell killing by CTLs is enabled by T-cell receptor (TCR) recognition of target antigens presented by HLA class I (HLA-I)/beta-2-microglobin (B2M) complexes on target cells." (PMID 36923305, 2022). "On the surface of tumor cells, the HLA class I complex consists of three components: the HLA class I heavy chain, B2M, and tumor-specific antigens." (PMID 36611830, 2022). "The analysis indicated that six genes (PIK3CA, CDC27, B2M, PTEN, SMAD4, and IL32) were strongly associated with tumor-infiltrating lymphocytes." (PMID 35903675, 2022).
tumor (continued). "In WT and B2m-/- B16 tumor-bearing lungs, around 40-50% IVneg CD8+ T cells expressed PD1 compared to only 10-20% IVpos CD8+ T cells in the circulation (“CD8”)." (PMID 36733396, 2022). "Previously, researchers identified that the loss-of-function mutation B2M was associated with MHC class I dysfunction, which indicated the potential molecular pathway of tumor cells escaping immunity." (PMID 36119033, 2022). "HLA-A complexes with beta-2 microglobulin to present viral and tumor-derived peptides on antigen-presenting cells for recognition by alpha-beta T-cell receptor on CD8+ T cells, guiding antigen-specific T-cell immune response to eliminate cells." (PMID 36923309, 2022). "In our experiments, HLA-I expression was significantly reduced in tumor cells by knocking out B2M or TAP genes." (PMID 36612246, 2022). "Not only immunogenic neoantigens affect the ability of T cells to identify and kill tumor cell, but mutations in immunologically relevant genes can also do, for example; mutations in JAK1, JAK2, B2M, and STK11genes." (PMID 34319027, 2021). "B2M levels were positively correlated with tumor grade, and expression of B2M in grade IV (also known as GBMs) was higher than that in grade II or grade III (also known as LGGs)." (PMID 33960680, 2021). "Loss of B2M and defective IFN-γ signaling are tightly associated with T cell-resistant phenotype and tumor-intrinsic determinants of resistance to immunotherapies." (PMID 33644048, 2021). "Not only immunogenic neoantigens, but also mutations in immunologically relevant genes, can affect the ability of T cells to identify and kill tumor cell, for example; mutations in JAK1, JAK2, B2M, and STK11genes." (PMID 34319027, 2021). "A complete loss of tumor MHC-I expression is typically the result of two genetic events, a mutation in one copy of the B2M gene combined with the loss of the second copy (B2M-LOH)." (PMID 34201655, 2021). "The role of B2M in tumor microenvironment and immune regulation need to be further elucidated by experiments." (PMID 33658560, 2021). "In Pat 25, B2M LOH and beta-2-microglobulin protein loss were both detected in the pre-treatment tumor and post-treatment tumor, with the patient primarily resisting therapy." (PMID 34194441, 2021). "Here, we demonstrate the prevalence of the copy neutral loss of heterozygosity (CN-LOH) involving HLA-I heavy chain and B2M gene in various human tumor cell lines and tissues." (PMID 34680201, 2021). "Our present study is distinct from previous studies that have mainly focused on exploring the role of B2M in tumor growth, invasion, and apoptosis, or on the role of B2M as a part of MHC‐I for antigen presentation." (PMID 33960680, 2021). "Alterations in the structure of MHC-I/II and the antigen presenting machinery, beta 2 microglobulin (B2M), prevents the identification and presentation of tumor antigens." (PMID 34268109, 2021). "One of the most common is loss of HLA class I antigen due to mutations in the beta-2-microglobulin gene (B2M), occurring in 30% of MSI tumours and rarely in MSS." (PMID 34302062, 2021). "The human leukocyte antigen (HLA) system, specifically MHC class I, is encoded by the HLA-A, -B, and -C genes, as well as by beta 2-microglobulin (B2M), and plays a central role in the tumor mechanisms of evading the patient’s immune system." (PMID 34445612, 2021). "For instance, tumor cells deficient in interferon-receptor signaling (JAK1/2) and antigen-presenting pathway (beta-2-microglobulin, B2M) have been reported to be associated with resistance to PD-1 blockade immunotherapy." (PMID 34095145, 2021). "Inactivating mutations of the beta 2 microglobulin gene (B2M) also play an instrumental role in immune evasion, influencing the assembly of MHC class I and thus altering tumor cell “visibility” for effector cells." (PMID 33567641, 2021).
tumor (continued). "Some patient-related and tumor-load variables such as age, comorbidities, beta-2-microglobulin levels (B2M), lymphocytosis or lymphocyte doubling time (LDT) are available in virtually all patients and remain valid in predicting TTFT." (PMID 33917885, 2021). "addressed this question and found CD4+ T cells being responsible for tumor rejection and the development of strong immune responses in B2M-null dMMR tumors." (PMID 34630437, 2021). "The AME of mutant B2M status on metastasis location is 0.6494 (~65%), meaning that on average a B2M-mutant tumor has a ~65% higher probability of having a peritoneal/peritoneal and lymphatic metastasis (p = 0.0006)." (PMID 34168989, 2021). "Mutation or deletion of beta-2-microglobulin (β2m), leading to MHC class I-deficiency, represents a major tumor escape strategy occurring in vivo in cancer patients, as well as in murine tumor models." (PMID 34910301, 2021). "Targeting B2M-related signaling pathway shows significant tumor killing activity in a wide range of cancer types, which provides a new strategy for tumor therapy." (PMID 33658560, 2021). "Firstly, the RNA‐sequencing data of all 33 TCGA tumor types and corresponding normal samples were obtained from TCGA and GTEx databases, respectively, to explore expression patterns of B2M in tumors." (PMID 33960680, 2021). "In a study of LS-CRC patients it was shown that B2M wild type tumours had a higher frequency of Tregs and hence increased immunosuppression as compared to the B2M mutant tumours." (PMID 34067951, 2021). "Increased B2M expression was observed in 12 out of 33 tumor types compared with that in corresponding normal tissues." (PMID 33960680, 2021). "Like Jak1/2 and B2m, Ankrd52 sgRNAs exhibited time-dependent enrichment in tumor cells in the presence of T cells, providing direct evidence that loss of ANKRD52 conferred resistance to T cell killing." (PMID 34853298, 2021). "Subgroup 1 had significantly low expression of MHC classes I and II and overall antigen processing machinery, including B2M, indicating very poor presentation of tumor neoantigens, if any." (PMID 32795913, 2020). "Mesenchymal stromal cells (MSCs) are crucial components of the tumor microenvironment, and MSCs-derived beta-2-microglobulin is involved in the processes of epithelial mesenchymal transition, migration and tumor growth in ESCC." (PMID 32698859, 2020). "TCV-treated patients showed a positive correlation on PC-1 among most of the cytokines and tumor markers B2M and FAS receptor." (PMID 32316978, 2020). "There was a positive correlation on PC1 for most of the cytokines suggesting the evolution of tumor-associated inflammation, and on PC2 for tumor markers (B2M, FAS receptor) along with Th2-associated cytokines." (PMID 32316978, 2020). "Tumor mass formation rate within 18 days of the first injection of wild type (WT), B2M−/−, CIITA−/−, and B2M−/− and CIITA−/− were 2/7, 3/7, 4/7, and 6/7, respectively." (PMID 32746912, 2020). "Administration of the CD122 (IL-2Rβ) IL2 pathway agonist bempegaldesleukin (known as NKTR-214), together with anti-PD-1, to B2M-knockout mice, markedly suppressed tumor growth and significantly increased mouse survival." (PMID 33276569, 2020). "Taking B2M as the reference gene, correlations were observed between the growing tumor area and peritumoral area for all studied desaturase genes." (PMID 32392704, 2020). "This collection of cytokines positively correlated with B2M, PD1 and TGFβ1 suggesting coexistence of pre-existing tumor-associated inflammation and immunosuppression." (PMID 32316978, 2020). "We also showed a weak positive correlation between TIL B7-H3 and B2M expression in tumor, a weak-to-moderate positive correlation between TIL B7-H3 and vital status, and a moderate positive correlation between TIL B7-H3 and CD8 density." (PMID 31692889, 2019). "Here, B2M-mutant tumours showed higher HEV densities compared with B2M-wild type tumours (median 0.139 vs 0.052 counts/mm2, p = 0.0116)." (PMID 31358939, 2019).